TRIM29 (tripartite motif containing 29)
Diseases named in the same sentence as TRIM29 in open-access papers (continued):
Sharing a sentence is not in itself a finding about the gene and the disease.
tumor (continued). "We have previously shown that normal urothelial cells transformed by As3+ form tumors which show strong staining for TRIM29, TFAP2A and P63 in the undifferentiated part of the tumor and weak staining in the areas of squamous differentiation." (PMID 36293167, 2022). "qPCR was used to measure the TRIM29 mRNA level in another cohort of CRC tissues and their normal tissue counterparts from 46 patients; among them, 40 had accurate information on the tumor side: 22 LSCC and 18 RSCC." (PMID 33495406, 2021). "In contrast, other TRIM proteins (e.g., TRIM3, TRIM29, and TRIM40) were found to have a tumor-suppressive effect." (PMID 34988104, 2021). "The expression of TRIM29 in colorectal cancer (CRC) tissue is significantly higher and correlates with tumor progression and poor prognosis." (PMID 34988104, 2021). "miR-335-5p and miR-15b-5p suppress the metastasis of NPC by targeting TRIM29 and inhibit the activity of the PI3K/AKT/mTOR signaling pathway; miR-122 inhibits tumor progression by downregulating TRIM29 and repressing the activity of PI3K/AKT signaling." (PMID 34988104, 2021). "The mobilization of the Gal-9/TRIM29/STING axis results in myeloid-cell-mediated T-cell suppression, which is beneficial for EBV-positive tumor cell survival." (PMID 32632113, 2020). "In contrast to TRIM29, TRIM58 represents a tumor suppressive member of the TRIM family which is characteristically downregulated in CRC tumors." (PMID 33066016, 2020). "Tumor-dissociated cells from TRIM29KO-1806-CarboR tumors showed no TRIM29 expression suggesting that TRIM29 knockout was consistently maintained throughout the tumor development in mice." (PMID 40420099, 2025). "TRIM29 promoted the degradation of IGF2BP1 by mediating its K48-type ubiquitination at the Lys440 and Lys450 sites, thereby decreasing the PD-L1 level and acting as a tumor suppressor to promote antitumor T-cell immunity." (PMID 39768197, 2024). "CST6, TRIM29, and CSTA (an ER target gene) possessed tumor-suppressive actions toward BC." (PMID 37370814, 2023). "Additionally, we noticed deep deletions of the TRIM29 and FA2H genes in the TCGA cohort, which is consistent with their reported tumor-suppressive roles in BC." (PMID 37370814, 2023). "In contrast, reduced expression of TRIM29 was noted in breast and prostate cancers and evidence for growth inhibition and tumor suppression was demonstrated in breast non-malignant and malignant cell lines." (PMID 24651077, 2014). "Notably, TRIM29 suppression was more evident in the luminal B subtype than in the luminal A. Indeed, it was previously suggested that TRIM29 might modulate the growth effects of 17β-estradiol on ER-positive mammary epithelial cells and function as a tumor suppressor in these cells." (PMID 24651077, 2014). "Furthermore, it is most likely that TRIM29 could regulate expression of ZNF750 and KRT5 in other tumors, as TRIM29 expression positively correlated with the expression of ZNF750 and KRT5 significantly in 18 tumor types, such as BLCA, CESC, HNSC, LUSC, PRAD, and SKCM." (PMID 37365152, 2023).
infection (14 papers, 2017 to 2026). The state of being infected such as from the introduction of a foreign agent such as serum, vaccine, antigenic substance or organism. "Taken together, our findings underscore that while TRIM29 is dispensable for barrier integrity, its deficiency in IECs restricts infections by enteric RNA viruses by enhancing IFN-λ3 and IL-18 production in primary IECs from mouse intestinal organoids." (PMID 39396665, 2025). "Together, these data demonstrate that IEC-specific TRIM29 deficiency is sufficient to control intestinal inflammation and infection by enteric rotavirus in suckling mice in vivo." (PMID 39396665, 2025). "In contrast, Trim29−/− mice were more susceptible to intranasal LPS challenge or infection with H. influenzae compared to wild type mice, caused by septic shock due to overproduction of cytokines." (PMID 33808506, 2021). "In line with this notion, Trim29−/− mice were less susceptible to infection with influenza A virus and reovirus, with lower viral loads in the lungs." (PMID 33808506, 2021). "Furthermore, alveolar macrophages derived from TRIM29-KO pigs showed reduced susceptibility to infection with PRV, VSV, and transmissible gastroenteritis virus (TGEV), highlighting their potential broad-spectrum antiviral activity against multiple viral pathogens." (PMID 41770824, 2026). "Conversely, small interfering RNA (siRNA)-mediated knockdown of TRIM29 in PAM cells enhanced N protein expression and viral titers at 16 h post-infection, reinforcing the notion that TRIM29 restricts PRRSV replication." (PMID 41251350, 2025). "TRIM29 exerts a vital role in macrophage activation in the respiratory tract in response to pathogen infection." (PMID 38787121, 2024). "These genes, especially for PVLR1, TRIM21, and TRIM29, are strongly related to immune responses to infection, which are warranted for further cellular and animal studies." (PMID 36353114, 2022). "The authors proposed that upon virus-infection TRIM29 interacts with STING at the perinuclear region, promoting its degradation by K48-ubiquitination at K288 and K337." (PMID 33808506, 2021). "Consistently, less HSV-1 virus was recovered in the brains, livers, and spleens isolated from Trim29-/- mice 2 and 4 days after infection, respectively, compared with WT controls." (PMID 29581886, 2018). "We also measured viral titers of adenovirus in lung homogenates by plaque-forming assay after infection, and found that the adenovirus load was reduced by 10,000-fold in Trim29-KO mice." (PMID 29038422, 2017). "Here, the authors show that TRIM29 is induced upon infection with DNA viruses, resulting in degradation of STING, decreased interferon signaling and increased pathogenicity in mice." (PMID 29038422, 2017). "Trim29-KO mice produced threefold to fivefold more IFN-I in the bronchoalveolar lavage fluid (BALF) than did WT mice at day 1 or day 3 post infection." (PMID 29038422, 2017). "Importantly, IEC-specific TRIM29-knockout mice were resistant to infection with enteric rotavirus in suckling mice and EMCV in adult mice in vivo." (PMID 39396665, 2025). "In addition, the reduction of NLRP6 and NLRP9b expression and upregulation of TRIM29 were first observed on 1 h in primary IECs from mouse intestine organoids of Trim29fl/fl mice after infection of EMCV or Rotavirus." (PMID 39396665, 2025). "This process may be the compensation to the degradative effect of TRIM29 to maintain STING expression during the initial stage of infection." (PMID 35871231, 2023). "Also, there were onefold to threefold more TNF-α and IL-6 detected in BALF from Trim29-KO mice, as compared to that in WT mice on day 1 or day 3 post infection." (PMID 29038422, 2017). "In addition, TRIM29 was found to inhibit the production of type I interferons in macrophage, and the deletion of TRIM29 can protect mice from infection with influenza virus, these results indicate that TRIM29 promotes the in vitro and in vivo growth of the influenza virus." (PMID 35458419, 2022).
infection (continued). "In responses to VACV-70, HSV-60, dsDNA, and cGAMP, Trim29-/- macrophages also produced significantly elevated CCL5 and CXCL10, the chemokines that are important to recruit immune cells to the site of infection and eliminate viral infection." (PMID 29581886, 2018). "The anti-PERK antibody, but not control IgG, precipitated TRIM29 in mouse cardiomyocytes from Trim29fl/fl or WTMyHC-Cre mice after infection with CVB3 or EMCV." (PMID 38664417, 2024). "However, the interaction between TRIM29 and PERK was disrupted in mouse cardiomyocytes from Trim29fl/fl or WTMyHC-Cre mice with mock infection." (PMID 38664417, 2024). "Additionally, Trim29-KO mice had higher concentrations of IFN-I, IL-6, and TNF-α in the serum than did their WT littermates after infection with HSV-1." (PMID 29038422, 2017). "By contrast, anti-TRIM29 Ab could not pull down NLRP6 or NLRP9b without infection, suggesting there were indeed interactions of TRIM29 with NLRP6 and NLRP9b in primary IECs from mouse intestine organoids under the condition of enteric RNA virus infection." (PMID 39396665, 2025). "We found that both NLRP6 and NLRP9b were induced in primary IECs from mouse intestine organoids of Trim29fl/fl mice after infection of EMCV or Rotavirus, further confirming that NLRP6 and NLRP9b are one of ISG and the degradation of NLRP6 and NLRP9b are mediated by TRIM29." (PMID 39396665, 2025). "Furthermore, Trim29–/– mice had higher concentrations of IFN-α and IFN-β in the heart than their Trim29+/+ littermates after infection with CVB3." (PMID 38664417, 2024). "TRIM29 could negatively regulate the infection of gram negative bacteria Haemophilus influenza by targeting NEMO and played a protective role in the host defense against bacterial infection." (PMID 31295956, 2019). "Intriguingly, the knockdown of TRIM29 markedly diminished the expression and activation of PERK but not IRE1α in human cardiomyocytes post-infection with the cardiotropic viruses CVB3 and EMCV." (PMID 38664417, 2024). "TRIM29 was shown to limit the abundance of NEMO under basal conditions, however, infection with reovirus, but not LPS, further upregulated TRIM29 levels promoting proteasomal degradation of NEMO by ubiquitination at K183." (PMID 33808506, 2021).
bacterial infections (6 papers, 2017 to 2022). "In murine alveolar macrophages, the E3 ubiquitin ligase Trim29 was found to negatively regulate the host response after bacterial infection." (PMID 29997615, 2018). "Recently, researchers have found that TRIM29, known as the E3 ubiquitin ligase, may modulate the activation of alveolar macrophages (AMs) in response to viral and bacterial infections via the degradation of NEMO, therefore limits the production of IFN-α/β as well as proinflammatory cytokines of AMs." (PMID 32292408, 2020). "TRIM29 is involved in IFN-γ signaling and cytokine signaling by playing an essential role in activating macrophage upon viral or bacterial infections within the respiratory tract." (PMID 36353114, 2022).
adenocarcinoma (3 papers, 2018 to 2021). A common cancer characterized by the presence of malignant glandular cells. "It was observed that high level of TRIM29 was significantly associated with worse OS in adenocarcinoma." (PMID 29552313, 2018).
inflammation (3 papers, 2018 to 2026). Aberrant reaction of the microcirculation characterized by movement of fluid and leukocytes from the blood into extravascular tissues. "In enterovirus-induced intestinal inflammation, TRIM29 targets and degrades NLRP6/NLRP9b, thereby suppressing the host innate immune response and facilitating viral replication." (PMID 41601651, 2026). "Thus, our insights into the role of TRIM29 in controlling enteric RNA virus-induced intestinal inflammation suggest potential therapeutic applications involving targeting TRIM29 to control gut diseases associated with SARS-CoV-2 infection." (PMID 39396665, 2025).
digestive system cancer (1 paper, 2018). A primary or metastatic malignant neoplasm involving any part of the digestive system. "First, we found that high level of TRIM29 was significantly related to a poor OS in digestive system cancers." (PMID 29552313, 2018). "Furthermore, TRIM29 was suitable to predict overall survival especially in Asians and digestive system cancers." (PMID 29552313, 2018).
intestinal diseases (1 paper, 2025). "Our findings indicate promise for potential therapeutic applications involving targeting E3 ligase TRIM29 to reduce intestinal inflammation in order to treat intestinal diseases such as viral gastroenteritis." (PMID 39396665, 2025).
neurological diseases (1 paper, 2019). "Among these genes, Ch25h, Trpa1, Cdkn1a, Ly6g6e, Six3, and Opalin are potentially associated with neurological diseases; Lcn2, Serpina3f, Lao1, Trim29, bcl3, and Gkn3 are associated with inflammatory response." (PMID 30804943, 2019).
respiratory diseases (1 paper, 2023). "For example, genes associated with respiratory diseases and cell proliferation (CA5B, ID2, CARD14 and TRIM29) were significantly altered." (PMID 36673815, 2023).
TRIM29 also shares sentences with these, for which no sentence is quoted: triple-negative breast carcinoma (3 papers); colorectal adenocarcinoma (2); anemia (1); Arthritis (1); cardiovascular diseases (1); cervix (1); cutaneous squamous cell carcinoma (1); dysplasia (1); Fibroadenoma (1); gastroenteritis (1); Hepatitis (1); hepatoblastoma (1); immune dysfunction (1); infectious disease (1); inflammatory bowel disease (1); influenza infection (1); Insulin resistance (1); intracranial aneurysm (1); kidney cancer (1); leukemia (1); mastitis (1); Merkel cell carcinoma (1); neurodegenerative disease (1); Obesity (1); phyllodes tumor (1); primary Sjögren’s syndrome (1); rectal cancer (1); renal cell carcinoma (1); renal diseases (1); serous carcinoma (1).
A further 3 diseases each share a sentence with TRIM29 in 1 paper.